ENTREP2 (endosomal transmembrane epsin interactor 2)
Synonyms: FAM189A1; KIAA0574; TMEM228
Tractability: Antibody: UniProt predicts a signal peptide or a membrane-spanning region.
Gene: Protein-coding gene on chromosome 15 (29,120,252 to 29,571,103, reverse strand). Ensembl gene ENSG00000104059.
Subcellular location: Membrane
Subcellular location (Human Protein Atlas): Nucleoplasm; Aggresome; Vesicles
Gene Ontology:
Cellular component: membrane
Genetic constraint (gnomAD): Loss-of-function variants: 30 observed, 36.21 expected, observed/expected ratio (o/e) 0.83, 90% interval 0.62 to 1.12. The upper end of that interval is the gene's LOEUF score, 1.12, which puts it in group 4 of 6, group 1 being the genes least tolerant of losing a copy. Missense variants: 679 observed, 640.05 expected, observed/expected ratio (o/e) 1.06, 90% interval 1 to 1.13. Synonymous variants: 325 observed, 284.2 expected, observed/expected ratio (o/e) 1.14, 90% interval 1.04 to 1.25.
Homologues: Orthologues: chimpanzee ENTREP2 (98% identical), macaque ENTREP2 (95% identical), pig ENTREP2 (80% identical), mouse Entrep2 (77% identical), rabbit ENTREP2 (71% identical), rat Entrep2 (65% identical), guinea pig ENTREP2 (64% identical), tropical clawed frog entrep2 (63% identical), dog ENTREP2 (60% identical), zebrafish fam189a1 (25% identical). Paralogues in human: ENTREP3 (34% identical), ENTREP1 (32% identical).
Diseases named in the same sentence as ENTREP2 in open-access papers:
ENTREP2 is named in the same sentence as 9 diseases in open-access papers, as found by Europe PMC text mining. Sharing a sentence is not in itself a finding about the gene and the disease. The quoted sentences say what the papers report.
lung disease (1 paper, 2025). "The remaining 11 genes in the region encode proteins associated with neurologic disorders (APBA2, CHRFAM7A, MTMR10, FAN1), skin and eye pigmentation or development (OCA2, HERC2, TJP1, TRPM1), nephritis (ARHGAP11B, MTMR10, FAN1), and lung disease (ENTREP2, NSMCE3)." (PMID 40013929, 2025).
ENTREP2 also shares sentences with these, for which no sentence is quoted: Arrhythmia (1 paper); breast carcinoma (1); cancer (1); nephritis (1); neurodevelopmental disorder (1); neurologic disorders (1); tobacco use disorder (1); tumor (1).